EGFR (epidermal growth factor receptor)
Diseases named in the same sentence as EGFR in open-access papers (continued):
Sharing a sentence is not in itself a finding about the gene and the disease.
cancer (continued). "Epidermal growth factor receptor (EGFR) protein is a well-studied oncological drug target as it is overexpressed in almost all types of cancers, including non-small cell lung cancer (NSCLC), breast, colon, prostate, etc.." (PMID 33803355, 2021). "The mechanism of GPCR involved in this cancer is the indirect activation of epidermal growth factor receptor (EGFR), by the release of epidermal growth factor (EGF) ligands from the surface which activates the intracellular signalling pathways." (PMID 33991433, 2021). "A number of ncRNAs have been demonstrated to be involved in regulating ABC transporters in drug-resistant cancer cells by regulating EGFR and its downstream signaling pathways." (PMID 35111681, 2021). "Among them, SVDNPHVC sequence or Disruptin, which is derived from the eight amino acid segment of EGFR, were reported to specifically bind to EGFR, preventing EGF-dependent EGFR dimerization that resulted in subsequent EGFR degradation in cancer cell lines." (PMID 34833427, 2021). "These include EMA- and FDA-approved erlotinib, gefitinib, afatinib and osimertinib for EGFR-mutant cancers." (PMID 32915318, 2021). "EGFR has been identified as a transcriptional co-activator for several cancer-promoting genes, including cyclin D1, nitric oxide synthase (iNOS), and cyclooxygenase-2 (COX-2)." (PMID 34295309, 2021). "The obtained pDA-PEG NPs were successfully used as a fluorescent label for molecular imaging of cancer cells at N1000 nm by functionalizing with Cetuximab (Erbitux) for targeting EGFRs on the cell membranes of EGFR-positive breast tumor MDA-MB-468 cells." (PMID 34372067, 2021). "Presence of elevated plasma level of PD-L1 has been shown to determine the response of various anti-cancer treatments including surgical reduction, chemotherapy, radiotherapy, anti-EGFR treatment, and anti-PD-1 immunotherapy." (PMID 34531847, 2021). "The dual-labeled protein was found to be a selective bioimaging and cytotoxic agent for EGFR-positive A431 cancer cells." (PMID 33897886, 2021). "Firstly, to investigate the CNVs of LANCL2 and EGFR genes in a panel of cancers, 32 studies of different cancer types in TCGA Pan-Cancer Atlas database (n = 10,967) were selected." (PMID 34461927, 2021). "In our PTT study, the MTT assay showed that the use of tAuNRs at 20 μg/mL concentration significantly increased cancer cell death (97.6 ± 3.2%) in the EGFR-positive cancer cell line CAL-27, following a significant rise in a well-averaged temperature." (PMID 34683944, 2021). "Molecular targeted drugs such as EGFR-TKIs were initially considered safe anti-cancer drugs with only minor AEs; however, it is known that targeted molecular therapeutic agents can cause serious AEs, including fatal illness." (PMID 33466795, 2021). "In this experiment, the localization of the FL-1/FL-2 nanostructures was monitored in A431 cancer cells expressing high levels of EGF receptors, and in HeLa and MCF-7 cancer cells with a lower EGFR density." (PMID 34064412, 2021). "The diverse roles of the EGFR in cancer progression have facilitated the development of anticancer therapies that interfere with EGFR-mediated effects, such as monoclonal antibodies and small-molecule tyrosine kinase inhibitors." (PMID 34360933, 2021). "PAR1 also interacts with epidermal growth factor receptor (EGFR) or ErbB/HER2 to regulate calcium pathway in cancer cells." (PMID 34066284, 2021). "Previous studies have shown that the drug activates c-Jun, Akt pathway, epidermal growth factor receptor (EGFR), cancer stem cells enrichment, epithelial-mesenchymal transition (EMT) enhancement and reduces autophagy." (PMID 34307125, 2021). "Afterwards, we took advantage of a patient-derived Cancer Stem Cell (CSC) line (L0627) that shows features typical of the classic molecular phenotype such as the overexpression of EGFR gene to validate the results also in a preclinical model closer to clinic." (PMID 34012924, 2021).
cancer (continued). "EGFR has an expression rate of 47–100% in human solid tumors and is therefore an attractive target for anti-cancer drugs." (PMID 33713216, 2021). "Among these kinases, the epidermal growth factor receptor (EGFR) attracted considerable attention as a valid target in cancer chemotherapy." (PMID 34770832, 2021). "Nbs have been produced to target cancer cell biomarkers (EGFR, human epidermal growth factor receptor 2 (HER-2) and prostate-specific membrane antigen (PSMA)) for nuclear imaging." (PMID 34575943, 2021). "Although paclitaxel can suppress the EGFR signaling pathways in different cancer cells most probably via matrix metalloproteinases, a direct suppression of EGF receptors, in our knowledge, was not previously reported." (PMID 34371754, 2021). "Although treatment with the EGFR-inhibitor cetuximab improves OS in HNSCC patients, therapeutic resistance poses a challenging problem and limits the success of effective anti-EGFR cancer therapies in the clinic." (PMID 34568028, 2021). "Epidermal growth factor receptor (EGFR), representing a promising new therapeutic target in cancer, is highly expressed in most human epithelial carcinomas and is expressed in 89%-100% of the samples collected from NPC patients." (PMID 34976847, 2021). "Analysis of premalignant and invasive cancers of DBPDE treated mice revealed that EGFR expression remains high in dysplastic and invasive cancer cells (respectively)." (PMID 34784403, 2021). "These MCF7-EGFR spheroids are a useful cancer model for the development of anticancer drugs, including EGFR-targeted therapeutics." (PMID 34884742, 2021). "CD44v8-10-expressing and undifferentiated cancer stem-like cells exhibit resistance to the monoclonal anti-EGFR antibody and sensitivity to SSZ." (PMID 33401672, 2021). "Increased expression of EGFR correlates with poor prognosis in CRC, and EGFR-targeted therapies have been shown to improve survival in EGFR-positive cancer patients." (PMID 34521767, 2021). "The epidermal growth factor receptor (EGFR) family member erb-b2 receptor tyrosine kinase 2 (ERBB2) is overexpressed in many types of cancers leading to (radio- and chemotherapy) treatment resistance, whereas the underlying mechanisms are still unclear." (PMID 33801244, 2021). "Further, EGa1 nanobody was coupled to the surface of the (mPEG/PDP-PEG)-b-p(HPMAm-Lacn) nanomicelles in order to enhance the specificity of the nanoscale carriers to EGFR-positive cancer cells and to improve recognition and intracellular uptake." (PMID 33981532, 2021). "EGFR overexpression is widely observed in a variety of cancer cells, and in some cases, its signal is critical for cell survival and tumorigenesis." (PMID 33707468, 2021). "Targeting epidermal growth factor receptor (EGFR) family of receptor tyrosine kinases (RTKs) have been approved as a successful approach for lung, breast and other cancers." (PMID 34012400, 2021). "D-Prop has 60-100-fold less beta-blocker activity than L-propranolol, but is equivalent in triggering PA/PDE4/PKA signaling and EGFR internalization in cancer cell lines." (PMID 34298835, 2021). "Activation of Bcl-2 is also involved in protective autophagy in cancer stem cells via EGFR signaling." (PMID 34829834, 2021). "This study provides the first data revealing a previously undiscovered connection between DR4 modulation and cell response to EGFR-targeted cancer therapy, particularly osimertinib, against EGFRm NSCLCs." (PMID 33664875, 2021). "Considering that HPV+ cancer induces higher EGFR express level upon study provides us a potential specific HPV+ cancer therapeutic method." (PMID 34646755, 2021). "Epidermal growth factor receptor (EGFR) amplification and/or mutation exist in different types of cancer and triggers higher interest in EGFR as a cancer therapeutic target." (PMID 34925034, 2021). "For instance, treatment of cancer cells lines with the anti-EGFR MAb nimotuzumab in vitro induced the upregulation MHC class I expression." (PMID 34211836, 2021).
cancer (continued). "GL and GlucoGL inhibit the interaction between PGRMC1 and EGFR, thereby suppressing EGFR-mediated signaling required for cancer progression." (PMID 34209885, 2021). "Experimental targeting of EGFR‐BRAF‐MEK in cancer organoids affected signaling and gene expression contingent on predictive KRAS/BRAF mutations and induced cell plasticity overriding default developmental trajectories." (PMID 34409732, 2021). "Our data suggest that the increased expression of EGFR in those tumors will be responsive to the treatment if cancer cells express Tspan6, which suppresses secretion of TGF-α." (PMID 34521767, 2021). "EREG and EGFR form a ligand and receptor, respectively, that are well-studied in cancer research, yet their prominent role in pain processing remained unclear." (PMID 33935700, 2021). "We found altered expression of several cancer-related molecules, as well as diminished expression of signaling receptors including Epidermal Growth Factor Receptor (EGFR), in CSMD1-expressing cells compared to control cells." (PMID 34404439, 2021). "In most of these cancer types the EGF receptor (EGFR) is over expressed but a basal physiological expression of the receptor can also be found in epithelial cells such as keratinocytes." (PMID 34012511, 2021). "Various monoclonal antibodies have been discussed to selectively target VEGFR, EGFR etc. in cancer therapies." (PMID 34944593, 2021). "The EGF receptor (EGFR) has a necessary role in the process of carcinogenesis and is of prognostic and therapeutic relevance in cancer." (PMID 33369107, 2021). "This cell line was selected because it is a classical model for studying effects of EGFR-targeted drugs, including erlotinib and cetuximab, on the EGFR-overexpressing cancer cells." (PMID 33748471, 2021). "Further, ectopic expression of miR-146b-5p improved EGFR-TKI-induced apoptosis in EGFR-TKI-resistant cells, EGFR-independent and -dependent osimertinib-resistant primary cancer cells (PE2988 and PE3479)." (PMID 34830377, 2021). "We have previously shown that PGRMC1 forms a unique heme-stacking functional dimer to enhance EGF receptor (EGFR) activity required for cancer proliferation and chemoresistance, and the dimer dissociates by carbon monoxide to attenuate its biological actions." (PMID 34209885, 2021). "Neratinib treats some forms of cancer, it inhibits the oncogenic intracellular signaling pathways of EGFR, HER2, and HER4, inhibiting autophosphorylation and activation." (PMID 34885957, 2021). "It knowns that promoted levels of the epidermal growth factor receptor (EGFR), a growth factor receptor tyrosine kinase, and/or its cognate ligands have identified as a common part of multiple cancer types and promote solid tumor growth." (PMID 33827480, 2021). "In fact, NRP-1 can lead to cisplatin-induced EGFR phosphorylation, an escape mechanism activated by cancer cells upon cytotoxic stress." (PMID 34359721, 2021). "EGFR inhibitors such as gefitinib, lapatinib and erlotinib, have been widely used clinically in several cancers such as NSCLC." (PMID 33955688, 2021). "One of the most relevant mAb targets with a higher clinical relevance is the epidermal growth factor receptor (EGFR), which is often overexpressed in a variety of cancer cells." (PMID 34400966, 2021). "For instance, in an EGFR mutation-driven resistant cancer that was exhibiting a novel mutant, FGFR combined suppression of FGFR and EGFR was effective in inhibiting cancer growth." (PMID 34737964, 2021). "Due to its crucial status related to cancer development, EGFR has been considered a potential drug target for many years." (PMID 34074193, 2021). "In cancer immunotherapy, malignant cells often overexpress receptors belonging to the epidermal growth factor receptor (EGFR) family that is required for cell growth and survival." (PMID 34276704, 2021).
cancer (continued). "MiR-302a has also been found to restore the response to cetuximab by inhibiting CD44-induced cancer stem cell (CSC)-like characteristics through EGFR-mediated MAPK and protein kinase B (AKT) signaling pathways." (PMID 35111681, 2021). "DHA potentiates the anti-cancer effects through a complementary reduction in phosphorylated EGFR, STAT3 and CAMKII proteins." (PMID 34829591, 2021). "An important mechanism by which cancer cells present uncontrolled epidermal growth factor receptor (EGFR) signaling is the evasion of receptor downregulation." (PMID 34249948, 2021). "Activation of bypass RTK signaling pathways is a central component of the early adaptive response to EGFR inhibition in cancer cells." (PMID 34853306, 2021). "To study the adaptive changes during targeted inhibition of oncogenic signaling we exposed cancer cells (n = 9) driven by diverse activated kinases (EGFR, MET, BRAF, HER2, ALK) to targeted drugs and performed transcriptional profiling using RNA-seq." (PMID 34535668, 2021). "Inhibition of EGFR confers higher sensitivity of cancer cells to ionizing radiations in preclinical studies on HNSCC." (PMID 33668730, 2021). "And GE11-Ori-Se NPs further killed cancer cells by disrupting the function of mitochondria, specifically inhibiting EGFR-mediated PI3K/AKT and Ras/Raf/MEK/ERK pathways." (PMID 34322025, 2021). "Our and other groups' work have demonstrated that the synthetic 12 amino acids peptide GE11, with the sequence of Y-H-W-Y-G-Y-T-P-Q-N-V-I, was an efficient epidermal growth factor receptor (EGFR) targeting peptide for EGFR overexpressed cancer cells." (PMID 33868396, 2021). "In the available studies, it has been demonstrated that LAPTM4B can promote EGFR signaling in cancer cells and is essential in the process of autophagy triggered by inactive EGFR." (PMID 32651973, 2021). "NTS, acting as a signal transmitter, has been shown to cause sustained activation of epidermal growth factor receptor (EGFR) and enhanced cancer growth." (PMID 33493519, 2021). "Oxycodone has been shown to stimulate cancer cell biological activities via regulating EGFR pathway." (PMID 34702181, 2021). "Further enrichment analysis showed that EGFR downstream pathway and cancer relative pathway are diversely activated in HPV+ cancer and HPV− cancer." (PMID 34646755, 2021). "PTMs catalyzed by B4GALNT3 confer stability to EGFR and avoids its degradation, contributes with EGFR signaling pathways that mediate the maintenance of stemness and consequently generates cancer cell growth, survival and attenuated differentiation." (PMID 34070747, 2021). "It is known that downregulation of E-cadherin by the epidermal growth factor receptor EGFR and the main regulator of EMT, SNAI1, is a prominent hallmark of cancer invasion." (PMID 34557494, 2021). "The heme-dimerized PGRMC1 interacts with the EGF receptor (EGFR) and cytochromes P450 to enhance cancer proliferation and chemoresistance, respectively." (PMID 34209885, 2021). "While RAS mutation is rare in BC, the RAS-RALGEF-RAL pathway propagates aggressive cancer phenotypes downstream of activated receptor tyrosine kinases such as epidermal growth factor receptor (EGFR) which is frequently overexpressed in TNBC." (PMID 34118960, 2021). "Our study suggested that exosomal cargos can be transferred between cancer cells with different genetic backgrounds and that these cargos possess bioactivity that can change the EGFR-TKI sensitivity of EGFR wild-type cells." (PMID 33671000, 2021). "EGFR overexpression in a wide range of cancers makes it a validated target for imaging and therapy using monoclonal antibodies." (PMID 33535661, 2021). "Based on the successful establishment of the NSCLC PDX model, we compared the expressions of vimentin, Ki67, EGFR, and PD-L1 proteins between cancer tissues and PDX models using hematoxylin and eosin staining and immunohistochemical staining." (PMID 33628593, 2021).
cancer (continued). "Its mechanism of action was at least in part mediated by inhibiting the activation of EGFR signaling and the expression of cancer stemness marker genes." (PMID 34879870, 2021). "The general anti-cancer mechanisms of cordycepin are regulated by the adenosine A3 receptor, epidermal growth factor receptor (EGFR), mitogen-activated protein kinases (MAPKs), and glycogen synthase kinase (GSK)-3β, leading to cell cycle arrest or apoptosis." (PMID 34443541, 2021). "Epidermal growth factor receptor (EGFR) is a promising target for the cancer therapeutics, against which several antibody clones have been developed and brought into therapeutic use." (PMID 33707468, 2021). "The result showed that EVs can be employed to target the EGFR expressing cancer tissue with nucleic acid drug for therapeutic purposes." (PMID 34575511, 2021). "To continue our efforts on targeted therapy, we used a HER2-binding peptidomimetic that was conjugated to a lipid to design liposomes that can be targeted to HER2/EGFR overexpressed cancer." (PMID 33800723, 2021). "For example, SCAMP3 protein was found to be an important regulator of EGFR trafficking and was suggested to play a critical role in EGFR-driven cancers." (PMID 33946771, 2021). "Gold nanoparticles include nanoshells, nanorods, and other nanoscale gold constructs utilized for drug delivery, early cancer cell identification by EGFR (epidermal growth factor receptor) overexpression, or Raman-based detection of epithelial cancers." (PMID 33435595, 2021). "PC cells express the proto-oncogene ErBB2, as well as type III mutant EGFR, designated EGFRvIII, which mediates the cell growth of several human cancer cells." (PMID 34064004, 2021). "Additional evidence showed that UCA1 promotes cell migration due to its ability to inhibit miR-7-5p, thereby enhancing the level of epidermal growth factor receptor (EGFR) in hypoxia-resistant cancer cells." (PMID 34298879, 2021). "Based on the findings that epidermal growth factor receptor (EGFR) is pivotal for cell growth in many cancers and is overexpressed in 67–100% of patients with BTC, EGFR inhibitors have been evaluated for treating advanced BTC patients." (PMID 32989241, 2021). "Binding of epidermal growth factor to its receptor triggers EGFR autophosphorylation and drives a complex intracellular signal transduction pathway, which modulates a set of cancer-related phenotypes." (PMID 35052426, 2021). "When using the reference material at VAFs of 0.5 and 1.0% with 20 ng of input, the Pan-Cancer Cell-Free Assay and Cobas-EGFR showed 100% detection." (PMID 34199654, 2021). "EGFR (also known as ErbB1) is a well-characterized RTK in studies pertaining to signal transduction as well as cancer initiation and progression." (PMID 33673213, 2021). "The top eight pathways selected for the EGFR mutation samples include salivary secretion, RAN degradation, ECM‐receptor interaction, cancer miRNAs, measles, glycerophospholipid metabolism, MAPK pathway, and focal adhesion." (PMID 33682961, 2021). "Amphiregulin, a ligand of the EGFR, encoded by the AREG gene, is upregulated in many cancers, determining cell growth, proliferation and migration through major intracellular signaling pathways triggered by receptor binding." (PMID 34063231, 2021). "The addition of TRAF2 to the DYRK1A–SPRY2–EGFR axis has broadened the complexity of regulation of EGFR and its dynamics in cancer signaling." (PMID 34117217, 2021). "Other cancer types modulate growth factor receptor signaling, such as TGFβ, EGFR, vascular endothelial growth factor receptor, and c-Met, through fucosylation." (PMID 34948129, 2021). "The overexpression also caused a decrease in expression of cancer-promoting factors EZH2, DNMT1, FOXM1, EGFR, PCNA, AURKA, YAP1, and CDH2." (PMID 34595169, 2021). "The epidermal growth factor receptor (EGFR) is a focus of increasing research attention in the field of cancer treatment." (PMID 34867408, 2021).